GLI1 (GLI family zinc finger 1)
Diseases named in the same sentence as GLI1 in open-access papers (continued):
Sharing a sentence is not in itself a finding about the gene and the disease.
breast carcinoma (continued). "Our data highlighting that the expression of GLI1 correlates with ESR1, pS2 and GREB1 using a publicly available dataset, suggest that GLI1 may represent a gene with implications in breast cancer." (PMID 27689403, 2016). "Moreover, a positive correlation between GLI1 and ERα expression was identified in breast cancer samples." (PMID 27689403, 2016). "NC inhibited the mRNA expression of Gli1 and Smo in these cells as well, suggesting that NC could inhibit the activation of Hh signaling in breast cancer." (PMID 27313840, 2016). "Furthermore, in a transgenic mouse model, the conditional expression of GLI1 was revealed to induce mammary tumors." (PMID 26744317, 2016). "Gli-1 mRNA level was increased in a number of breast cancer cell lines, including MDA-MB-453 (TN), MDA-MB-231 (TN and basal type B), BT20 (basal type A), MCF10A (benign breast cancer cell line) and SKBR3 (HER2+) in comparison to a primary human mammary epithelial cells (HMEC)." (PMID 26389956, 2015). "These evidences supported that CXCR4 is also a direct target gene of GLI1 in breast cancer cells." (PMID 26413813, 2015). "Increased expression of GLI1 was also found in breast cancers compared to benign breast tissues." (PMID 26633513, 2015). "Gli-1 upregulation correlates with poor prognosis of triple negative and basal like breast cancers." (PMID 26389956, 2015). "Some studies correlated overexpression of Gli-1 to ER-positive and TN subtypes of breast cancer." (PMID 26389956, 2015). "Hedgehog pathway members PTCH, Gli-1, and Gli-2 have been reported to be more highly expressed in normal mammary stem cells and their malignant counterparts, breast cancer stem cells, compared to more differentiated breast cancer cells." (PMID 25276795, 2014). "We have shown here evidence of crosstalk between the GLI1 signaling and NFκB pathways in both EMT and claudin-low cell lines, indicating that activated GLI1, could be a mechanism that also operates in breast cancer stem cells." (PMID 25252859, 2014). "Our results uncover crosstalk between NFκB and GLI1 signals and suggest that targeting these pathways may be effective against the claudin-low breast cancer subtype." (PMID 25252859, 2014). "Because ER expression was correlated with Gli1, we then asked whether estrogen could influence Shh pathway activation in breast cancer cells." (PMID 24889938, 2014). "In this study, we investigated whether estrogen could promote CSC maintenance and EMT through Gli1 in human ER-positive breast cancer cell lines MCF-7 and HCC1428, and ER-negative cell lines BT549 and MDA-MB-231." (PMID 24889938, 2014). "Firstly, we investigated whether estrogen-treated breast cancer cells exhibited Gli1-dependent changes in cell motility using a wound healing assay in MCF-7 and HCC1428 cells." (PMID 24889938, 2014). "Given that the expression of SHH in various breast cancer cell clines and the nuclear translocation of Gli-1 are suppressed by NCTD, it may imply that NCTD can be used to target renewal signaling against CSCs." (PMID 24073010, 2013). "Elevated GLI1 expression and its role in a number of cancers has been widely reported, including a recent study that the conditional expression of GLI1 in mouse mammary glands results in mammary tumours." (PMID 21505458, 2011). "Our observations indicate that not only GLI1 expression but more important its implication in the Hh signalling pathway might be a more precise characteristic of human breast cancers." (PMID 19706168, 2009). "Our study presents a systematic expression analysis of GLI1 in human breast cancer." (PMID 19706168, 2009). "To analyse the role of GLI1 in human breast cancer we carried out an initial realtime PCR analysis and found increased levels of GLI1 mRNA expression comparing the malignant mammary cell lines SKBR3, MDA-MB468, BT20, MDA-MB231 and MDA-MB435s to a set of benign mammary cell lines (HMEC and MCF12A)." (PMID 19706168, 2009).
breast carcinoma (continued). "A significant correlation between increased expression of both SHH and GLI1 in human breast cancer would support the hypothesis that aberrant Hh signalling contributes to breast cancer development or progression." (PMID 19706168, 2009). "Therefore we performed a systematic expression analysis of GLI1 in human breast cancer on the mRNA and protein level and correlated GLI1 expression with clinicopathological patient characteristics." (PMID 19706168, 2009). "In this study we questioned whether GLI1 expression might also be important in human breast cancer development." (PMID 19706168, 2009). "GLI1 gene staining in breast cancer tissues appears lighter compared to adjacent tissues, suggesting lower GLI1 expression levels in breast cancer tissues, thus confirming the hypothesis from previous experimental data that gli1 gene functions as a tumor suppressor gene." (PMID 39483334, 2024). "Therefore, inhibition of GLI1-target agents may be effective for breast cancer treatment in the future." (PMID 36046646, 2022). "Thus, GLI1 activation by SMO-dependent or -independent mechanisms in breast cancer cells could promote EMT-like changes and stemness acquisition, resulting in enhanced metastatic potential and chemoresistance." (PMID 34572373, 2021). "Additionally, inhibiting the GLI1 expression could efficiently mitigate tumor growth and migration and showed its therapeutic potential in breast cancer management." (PMID 33494284, 2021). "In addition, the interaction between PI3K and HH has been reported to be important for tamoxifen resistant breast cancer and combined targeting of both GLI1/2 (using the GLI antagonist GANT61) and PI3K/mTOR (using PI103) synergistically increased apoptosis and reduced tumor growth." (PMID 32245491, 2020). "In addition, Gli1 expression correlates with unfavorable prognosis of breast cancers." (PMID 32430068, 2020). "Furthermore, the expression of Gli1 was significantly increased in breast cancer tissues." (PMID 32150666, 2020). "Hence, targeting SHH/GLI1 axis may provide a plausible therapeutic implication for metastatic breast cancer patients." (PMID 31036836, 2019). "Although activation of the Hh pathway by somatic mutations is rare in breast cancer, non-canonical Hh activation through transcriptional upregulation of GLI1 is seen downstream of multiple oncogenic pathways, including the PI3K-Akt-mTOR pathway, K-Ras, c-Myc, Wnt-beta catenin and TGFβ." (PMID 31394751, 2019). "Additionally, a novel alternatively spliced version of GLI1, namely truncated GLI1 (tGLI1) may play a critical role in breast cancer invasiveness by upregulating vascular endothelial growth factor-A and CD24." (PMID 31394751, 2019). "Targeting Gli-1 could be a potential strategy to suppress breast cancer stem cells." (PMID 29734730, 2018). "Several types of carcinoma have been reported to have aberrant activation of Gli1, including hepatocellular carcinoma, gastric cancer, lung cancer, breast cancer and basal cell carcinoma, indicating the dysregulation of Gli1 may contribute to malignant biological behavior." (PMID 29113369, 2017). "In addition, researchers have confirmed that inhibiting the Gli1 expression could effectively attenuate tumor growth and migration and indicated its potential role as a therapeutic target in breast cancer management." (PMID 29113369, 2017). "The over expression of Gli1 could predict poor survival in patients with breast cancer." (PMID 29113369, 2017). "Thus, the role of GLI1 for the proliferation of ERα-positive breast cancer cells may be exploited for therapeutic purposes, and drug targeting of GLI1 could enhance the tamoxifen efficacy in the treatment of breast cancer." (PMID 27689403, 2016). "Thus, the mechanisms by which normal duct epithelium suppresses the transcriptional activity of nuclear GLI1 and by which breast cancer cells activate it remain unclear." (PMID 26744317, 2016).
breast carcinoma (continued). "Therefore GLI1 may be a potential therapeutic target and moreover, could also act as a prognostic marker in breast cancer." (PMID 27689403, 2016). "Overall, our findings suggest that GLI1 may represent a new important prognostic marker in breast cancer, thereby supporting the use of combined therapies involving HH pathway inhibitors and endocrine treatment in breast cancer." (PMID 26927093, 2016). "Some examples are breast cancer, where high GLI1 expression measured in a TMA containing 204 tumor samples was associated with poor prognosis and progressive stages of disease or bone and soft tissue sarcomas, where higher GLI1 expression correlated with more aggressive outcomes." (PMID 26258070, 2015). "Given that GLI1 enhanced the lung metastasis of mouse 4T1-Luc cells, we assumed that GLI1 might up-regulate the expression of gene(s) responsible for the metastasis of human breast cancer cells." (PMID 26413813, 2015). "Deregulation of the Shh–GLI1 pathway has been showed to lead to tumorigenesis and aggressive phenotypes (progression, metastasis and therapeutic resistance) of numerous cancer types such as basal cell carcinomas, colorectal carcinoma, breast cancer, and bone and soft tissue sarcomas." (PMID 26258070, 2015). "However, whether Gli1 is involved in estrogen-induced stemness and invasiveness in breast cancer remains uninvestigated." (PMID 24889938, 2014). "In this study, we for the first time demonstrated that genistein has multiple anti-breast cancer cell effects, not only suppressing proliferation and inducing apoptosis of the cancer cells, but also specifically inhibiting the cancer stem cells by downregulating the Hedgehog–Gli1 pathway." (PMID 24331293, 2013). "Furthermore we correlated GLI1 expression with histopathological and clinical data to evaluate whether GLI1 could represent a new prognostic marker in breast cancer treatment." (PMID 19706168, 2009). "GLI1 is an important transcriptional regulator within the Hh signalling cascade and may represent a novel biomarker in the development of human breast cancer with possible applications for future multimarker panels for early detection, molecular sub typing or personalised treatment." (PMID 19706168, 2009). "Since GLI1 is supposed to be a direct downstream target of Hh signalling in model organisms like Drosophila we wanted to decipher whether there is a correlation between the SHH and GLI1 expression patterns in human breast cancer and normal human breast tissues." (PMID 19706168, 2009). "Assuming that GLI1 might be involved into human breast cancer development and further proposing that GLI1 is activated through upstream members of the Hh signalling cascade, the mentioned Hh inhibitors could offer new drugs in the treatment of breast cancer as well." (PMID 19706168, 2009). "Our data raise the hypothesis that GLI1 represents a candidate oncogene in human breast cancer." (PMID 19706168, 2009). "Thus GLI1 protein expression measured e.g. by an IHC based scoring system might have an implication in future multi-marker panels for human breast cancer prognosis or molecular sub typing." (PMID 19706168, 2009). "In pancreatic and breast cancers, AKT-driven GLI1 activation promotes tumour stemness and chemoresistance, even in the presence of SMO inhibitors." (PMID 40426308, 2025). "Integrin α11 which was consistently up-regulated by cooperative interactions of HIF1α, GLI-1, and EZH2 in a positive feedback circuit, resulted in drug resistance, CSC increase and EMT in breast cancer cells." (PMID 38664825, 2024). "These include EMT (TWIST1, SNAIL1, RUNX1, RUNX2, HIF1, and NOTCH1), breast cancer maintenance (OCT4, SP1, GATA1, ATF1, FOXO3a, ELK1, VDR, and NRF1), pro-metastatic responses (SMAD2/3, HNF1a, GLI1, NANOG, YY1, MYB1, and AP1), and immune modulation (STAT1/3)." (PMID 38398186, 2024).
breast carcinoma (continued). "Regarding TGF-β signalling, it has been shown that this pathway can induce the expression of GLI1 and GLI2 transcription factors in several cancer cell lines, such as pancreatic ductal adenocarcinoma and breast cancer." (PMID 36765685, 2023). "Their expression levels were all higher in breast cancer tissue than in normal breast tissue, with more than a two-fold difference for SMO, GLI1, and GLI2." (PMID 36142286, 2022). "We found that normal breast tissue and breast cancer tissue expressed significantly different levels of SHH, PTCH1, SMO, GLI1, and GLI2 (p < 0.05)." (PMID 36142286, 2022). "First, we analyzed the expression of SHH, PTCH1, SMO, GLI1, and GLI2 in normal breast and breast cancer tissues through the Oncomine database." (PMID 36142286, 2022). "We found that, like in CLL and breast cancer, in MF fibrocytes and LDCs phosphorylated STAT3 binds to and activates the GLI1 gene promoter." (PMID 35595725, 2022). "TNBC has higher basal expression levels of the Hh signaling pathway gene such as GLI1 and GLI2, which are downstream of Hh ligands, than other breast cancers." (PMID 35744786, 2022). "Conversely, the silencing of GLI1 and OPN enhanced the sensitivity of breast cancer cells to all three chemotherapeutics." (PMID 34638233, 2021). "Our data suggest that the GLI1 gene, also activated by STAT3 in breast cancer cells, can be activated by either phosphoserine or phosphotyrosine STAT3." (PMID 33747356, 2021). "We also demonstrated that simultaneous targeting of FGFR1 and GLI1 using GANT61 and AZD4547 inhibitors significantly decreases breast cancer invasion and metastasis, suggesting new approaches for clinical studies." (PMID 34722544, 2021). "Many studies support the claim that target genes GLI1 and GLI2 are involved in breast cancer cell proliferation, survival, migration, invasion, EMT, angiogenesis, and osteolytic metastasis." (PMID 31979397, 2020). "Separate from GLI1, we observed tGLI1-mediated upregulation of matrix metalloproteinase-2 (MMP-2) and MMP-9 which facilitate breast cancer invasion through degradation of the extracellular matrix." (PMID 32957513, 2020). "Wang and colleagues found that in human estrogen receptor positive breast cancer cells, estrogen promotes a CSC and EMT phenotype via activation of Gli1, a downstream effector of the Hh pathway." (PMID 32391382, 2020). "Utilization of the A3 adenosine receptor agonist, resulted in a decrease in breast cancer stem cell survival which correlated with a decrease in activated ERK1/2 and GLI1." (PMID 32245491, 2020). "There is a relationship between CD24 and Sonic hedgehog (SHH), as knocking down CD24 in breast cancer cells have demonstrated increased proliferation, invasion, and tumorigenicity through higher expression of SHH, GLI1, and MMP2." (PMID 32426267, 2020). "Published reports indicate a similar disconnect between Gli1 inhibition and cell proliferation for HPI-1 in T2 breast cancer cells." (PMID 31137846, 2019). "Finally, examination of human cancer samples showed that expression of PRMT5 and MEP50, as well as GLI1 target genes was upregulated in small cell lung carcinoma, gastric cancer, other known HH signal-activated cancers including skin basal cell carcinoma 3 and breast cancer." (PMID 30675521, 2019). "Doxorubicin (1 μM) was found to significantly stimulate the expression of PLG (plasminogen, downregulated by Twist1 inhibitors; ANGPT2 (involved in breast cancer metastasis in brain); IGF-1 (a stimulator of TWIST1) and GLI1 (activated upon TWIST1 activation)." (PMID 31331001, 2019). "Expression of estrogen receptorpositively correlated with GLI1 and ALDH1 in tissue microarray from 100 human breast cancer samples." (PMID 31394751, 2019). "The ΔNp63 isoform of p63, which is the predominant isoform expressed in mammary epithelium, maintains the multipotent stem cell population in normal epithelium as well as in breast cancer; ΔNp63 drives expression of Hh ligands, PTCH1, GLI1 and GLI2." (PMID 31394751, 2019).
breast carcinoma (continued). "The present study explored relationship between SHH/GLI1 axis and EMT (Ecadherin, Vimentin and Snail) markers in Pakistani breast cancer cohort." (PMID 31036836, 2019). "For example, USP37 can interact with Hedgehog pathway components Smo and Gli-1 to stabilize these proteins and is essential for stemness maintenance, cell invasion, and EMT in breast cancer." (PMID 31998374, 2019). "Gli-1 is crucial for hypoxia-induced epithelial-mesenchymal transition (EMT) and invasion of breast cancer." (PMID 29734730, 2018). "Furthermore, a distinct subgroup of breast cancer (triple negative breast cancer/TNBC) characterized by high recurrence, metastasis formation, and, thus, a very poor prognosis, displayed aberrant Hh pathway activity caused by elevated expression of SMO and GLI1." (PMID 29695137, 2018). "However, the functional and prognostic significance of Gli1 in breast cancer still remains unclear." (PMID 29113369, 2017). "Considering breast cancer is a typical hormone-related cancer, we performed pooled analysis on correlations between Gli1 expression and three specific immunohistochemical parameters (PR, ER, HER-2) in breast cancer patients." (PMID 29113369, 2017). "The same assay was also performed using two additional ERα-positive breast cancer cell lines, ZR751 and T47D, resulting in a similar downregulation of ERα, IL20 and pS2 by GLI1 knockdown." (PMID 27689403, 2016). "Interestingly, the percentage of cells displaying nuclear GLI1 staining positively correlated with ErbB2 expression in carcinoma samples (p = 0.027), and this result suggests the involvement of Hh pathway activation in the development of ErbB2-positive breast cancer." (PMID 26843616, 2016). "Expression analysis of key markers of the activity of the HH signaling pathway i.e. GLI1 and PTCH1, revealed higher expression in the tamoxifen resistant LCC2 breast cancer cells compared to the parental, tamoxifen sensitive MCF7 cells." (PMID 27689403, 2016). "Here, we present in vitro data using a number of different breast cancer cell lines, demonstrating the modulatory effect of TAM on cellular proliferation and expression of HH signaling components, in particular GLI1." (PMID 26927093, 2016). "Next, the in vitro effects of two Hh signaling pathway inhibitors on breast cancer cell lines were evaluated using the Smoothened (SMO) antagonist GDC-0449 and the direct GLI1 inhibitor GANT-61." (PMID 26843616, 2016). "Target genes of GLI1 are induced, leading to contribute the cellular properties, such as the proliferation (by AEBP1) and metastasis (by CXCR4) of breast cancer cells." (PMID 26744317, 2016). "We here present evidence that GLI1 up-regulates the expression of CXCR4, CXCR7 as well as LCP1/L-PLASTIN, an actin-binding protein crucial for CXCL12/CXCR4 signaling, in breast cancer cells." (PMID 26413813, 2015). "GLI1 also transcriptionally regulated the expression of the potent pro-angiogenic secreted molecule, cysteine-rich protein 61 (CYR61) in breast cancer, which resulted in highly angiogenic tumors that were spontaneously metastatic." (PMID 26633513, 2015). "In breast cancer cells, we found that GLI1 and GLI2 up-regulated these expressions, while treatment with GLI-specific inhibitor GANT61 reduced the expressions." (PMID 26413813, 2015). "These evidences indicated that, in addition to CXCR4, the expression of CXCR7 and LCP1 was also in the downstream of GLI1 and GLI2 in breast cancer cells." (PMID 26413813, 2015). "Our data is in contrast to previous siRNA experiments, where silencing of GLI1 resulted in increased apoptosis and reduced level of anti-apoptotic Bcl-2 in HCC, glioma and breast cancer cells." (PMID 25544756, 2015). "Quantitative analysis using Real-Time RT-PCR on clinical samples, containing 4 Triple Negative and Basal-Like breast cancer as well as six HER2 positive cases, showed higher Gli-1 expression in tumors compared with matched normal tissue." (PMID 26389956, 2015).